PMEL (premelanosome protein)
Diseases named in the same sentence as PMEL in open-access papers (continued):
Sharing a sentence is not in itself a finding about the gene and the disease.
melanoma (continued). "MITF level and expression of MITF-dependent pigmentation-related genes, MLANA, PMEL, TYR, and DCT, in drug-naïve and vemurafenib- or trametinib-treated patient-derived melanoma cell lines and their drug-resistant counterparts were analysed and referred to genomic alterations." (PMID 31354817, 2019). "The observation of a melanocyte-like phenotype was supported by the fact that shRNA-Tsc2 + Cdkn2a sphere cells that were differentiated in neural-crest differentiation medium showed similar positive staining for CATHEPSIN K, PMEL, MITF and MART-1 to the B16F1 melanoma cell line." (PMID 29133867, 2017). "However, antibodies targeting either melanoma proteins, such as HMB-45 (anti-gp100/Pmel17/PMEL) and PNL2, or anti-oestrogen receptor alpha detect a variable subpopulation of cells within nodules, which tend to have the epithelioid phenotype." (PMID 25978616, 2015). "Additionally, we reported a GH-induced upregulation and GHRKD-induced suppression of MITF-regulated melanogenesis pathway genes—TYR, TYRP1, TYRP2/DCT—as well as melanosomal markers PMEL (gp100) and MLANA, in multiple melanoma cell lines, xenograft models, and in silico analyses." (PMID 31547367, 2019). "A previous study found that PMEL was an MITF target gene in melanocytes and melanoma, with its mRNA levels being enhanced upon transfer of wt MITF and blocked by a dominant negative form of MITF, which indicated that the expression level of MITF was necessary for the PMEL gene transcription." (PMID 27690000, 2016). "The non-immune cell clusters were made up of melanoma cells (MLANA, PMEL, MITF, DCT), endothelial cells (VWF, PECAM1) and fibroblast cells (COL1A1, COL3A1)." (PMID 36433984, 2022).
metastatic melanoma (62 papers, 2007 to 2026). A melanoma that has spread from its primary site to another anatomic site. "As for PMEL (premelanosome protein), amyloid extracellular aggregates were found in metastatic melanoma together with other proteins that aid amyloid maturation into fibrils." (PMID 36601538, 2022). "Here, using secretome analyses, we reveal the extracellular accumulation of amyloidogenic proteins, i.e. premelanosome protein (PMEL), in metastatic melanoma, together with proteins that assist amyloid maturation into fibrils." (PMID 32749065, 2020).
PEComas (55 papers, 2004 to 2026). "tRCC and PEComas have highly overlapping epithelioid morphologies and immunophenotypes, including expression of melanocytic lineage genes and lysosomal markers (PMEL, MelanA, Cathepsin K, GPNMB) that are canonical MiT/TFE transcriptional targets." (PMID 41044182, 2025).
uveal melanoma (33 papers, 1998 to 2025). A melanoma derived from melanocytes of the uveal tract. "PMEL is a co-expression gene with BAP1 (BAP1 loss is common in uveal melanoma UM and is associated with a worse prognosis)." (PMID 34722301, 2021).
vitiligo (26 papers, 2010 to 2025). Generalized well circumscribed patches of leukoderma that are generally distributed over symmetric body locations and is due to autoimmune destruction of melanocytes. "Both vitiligo associated genes (PMEL, TYRP1, DCT & MLANA) and PD-L1 had mRNA levels near the median value observed across the dataset." (PMID 30832716, 2019). "Similarly, in vitiligo, CD8+ T cells target antigens from melanosomal proteins such as PMEL, MLANA/MART1, TYR, TYRP1, and DCT." (PMID 37339630, 2023).
cutaneous melanoma (18 papers, 1998 to 2026). A primary melanoma arising from atypical melanocytes in the skin. "Pathogenic germline variants in pigmentation genes linked to albinism were identified in 11 individuals (7%), including three truncating variants in PMEL, reinforcing the role of pigmentation pathways in cutaneous melanoma susceptibility." (PMID 41673532, 2026). "Notably, many of these genes, such as MLANA, PMEL (HMB45) and S100, correspond to well‐established immunohistochemical markers for cutaneous melanoma." (PMID 41017066, 2025). "PMEL expression level was proposed to be a negative prognostic marker in Skin Cutaneous Melanoma (SKCM)." (PMID 36768787, 2023).
lymphangioleiomyomatosis (14 papers, 2012 to 2026). A multifocal neoplasm with perivascular epithelioid cell differentiation affecting almost exclusively females of child-bearing age. "PMEL, a gene involved in lymphangioleiomyomatosis (LAM) was underexpressed." (PMID 37208747, 2023). "Likewise, gp100/PMEL proved a credible target for T cells in lymphangioleiomyomatosis (LAM)." (PMID 40630962, 2025).
metastatic tumor (7 papers, 2012 to 2024). "In the present results, melanocyte protein PMEL was designated differentially expressed and more abundant in metastatic than non-metastatic tumors." (PMID 26305875, 2015).
pigmentary glaucoma (3 papers, 2020 to 2023). Pigmentary glaucoma is a type of secondary open-angle glaucoma characterized by heavy homogenous pigmentation of the trabecular meshwork, iris transillumination defects, and pigment along the corneal endothelium (Krukenberg spindle). "While human pedigrees of pigmentary glaucoma show that mutations in PMEL’s repeat domain lead to dominant inheritance, until this work, no animal model was available to confirm this pattern or investigate its aetiology." (PMID 37833870, 2023). "Pigmentary glaucoma has recently been associated with missense mutations in PMEL that are dominantly inherited and enriched in the protein’s fascinating repeat domain." (PMID 37833870, 2023). "Pigmentary glaucoma is a complex form of vision loss with only a single known causative gene, PMEL (encoding the premelanosome protein), which was identified by a recent international collaboration considering patients from multiple countries and lineages." (PMID 37833870, 2023). "The repeat domain is homologous in zebrafish and human PMEL, a location where two-thirds of the human pigmentary glaucoma patient mutations cluster." (PMID 37833870, 2023). "Moreover, the dominant inheritance associated with PMEL in pigmentary glaucoma in patients, and in zebrafish and chicken pigmentation, suggests that when even a minority of the PMEL protein molecules are dystrophic that is sufficient to induce disease." (PMID 37833870, 2023). "For example, PMEL mutations are linked to pigmentary glaucoma in humans." (PMID 32433666, 2020). "The dominant missense mutations in PMEL, including in pigmentary glaucoma patients, suggest the hypothesis that mutant PMEL amyloid in heterozygous animals has intermolecular interactions that disrupt the function of the normal PMEL protein." (PMID 37833870, 2023). "PMEL-KO mice have only a very subtle pigmentation deficiency, and human PMEL variants are associated with pigmentary glaucoma but not OCA." (PMID 36334630, 2022).
Pulmonary lymphangioleiomyomatosis (3 papers, 2017 to 2025). "The other gene (PMEL) encodes for a protein that is highly expressed by cells associated with pulmonary lymphangioleiomyomatosis, a potentially lethal cystic lung disease." (PMID 37208747, 2023).
renal angiomyolipomas (3 papers, 2014 to 2023). "After applying Pearson analysis, we identified five proteins (out of the 34 intersected DE proteins) positively correlated with the maximum renal angiomyolipoma (p < 0.05), namely, PCSK1N, PMEL, HK1, GOT2 and SPTBN2." (PMID 36891236, 2023). "Among the genes upregulated in the TSC2−/− organoids were: MLANA, PMEL, GPNMB, CTSK, and ACTA2, with median expression fold change 121x-, 88x-, 34x-, 14x-, 9.5x, respectively, all of which are known to be highly expressed in the renal angiomyolipoma." (PMID 34764250, 2021).
deafness (2 papers, 2015 to 2021). An inherited or acquired condition characterized by the complete loss of the ability to hear from one or both ears. "Across species, the genes identified with deafness or white pigmentation patterns include MITF, PMEL, KIT, EDNRB, CDH23, TYR, and TRPM1 in dog, cat, horse, cow, pig, sheep, ferret, mink, camelid, and rabbit." (PMID 26664958, 2015). "Although the piebald locus is caused by MITF and the merle locus is caused by PMEL in dogs, and the white spotting locus is caused by KIT in cats, the genes responsible for the pigment-associated deafness in these species have not yet been identified." (PMID 26664958, 2015).
polycystic kidney disease (2 papers, 2020 to 2024). A usually autosomal dominant and less frequently autosomal recessive genetic disorder characterized by the presence of numerous cysts in the kidneys leading to end-stage renal failure. "Therefore, for our analyses we chose a peptide antibody against an amino acid sequence containing the PKD (polycystic kidney disease) domain region of the human PMEL with high sequence homology to the bovine PMEL protein." (PMID 32668786, 2020).
mouth ulcers (1 paper, 2023). "The proteins encoded by eight genes (PMEL, ARFIP1, FAM213A, GLUL, CADM2, FAIM3, RIPK2, and DECR1) have only one SNP instrumental variable and have a association with mouth ulcers using the Wald ratio method." (PMID 37369724, 2023).
oculocutaneous albinism (1 paper, 2025). Oculocutaneous albinism (OCA) describes a group of inherited disorders of melanin biosynthesis characterized by a generalized reduction in pigmentation of hair, skin and eyes and variable ocular findings including nystagmus, reduced visual acuity and photophobia. "Furthermore, biallelic truncating variants in the PMEL gene have been identified in humans, leading to a novel form of oculocutaneous albinism (OCA), characterized by a unique age-dependent pigment recovery phenomenon." (PMID 41227465, 2025).
retinal degeneration (1 paper, 2015). Degeneration of the retina. "However, unlike PMEL, both myosin VIIa and Rep1 are also expressed in the photoreceptors and so trafficking defects within the photoreceptors, as well as in the RPE, contribute to the observed retinal degeneration." (PMID 25690007, 2015).
Waardenburg syndrome (1 paper, 2011). A disorder characterized by varying degrees of deafness and minor defects in structures arising from neural crest, including pigmentation anomalies of eyes, hair, and skin. "Thus, possible candidates for white coat colour (KIT on BTA6, KITLG on BTA5, PMEL on BTA5, TYR on BTA29) and other Waardenburg syndromes (WS) including PAX3 (WS1, WS3; on BTA2), EDNRB (WS4a; on BTA12), EDN3 (WS4b; on BTA13) and SOX10 (WS2e, WS4c; on BTA5) could be clearly excluded." (PMID 22174915, 2011).
tumor (683 papers, 1996 to 2026). "The Melanoma Associated Antigen Gene (MAGE) family proteins, tyrosinase, and the Premelanosome Protein gp100 are UM tumor-associated antigens (TAA) that are recognized by cells of the immune system." (PMID 34830841, 2021). "Indeed, class II tumor-associated antigens have been identified including mucin 1, tyrosinase, premelanosome protein gp100, survivin, telomerase reverse transcriptase, and many others." (PMID 33708224, 2021). "These MRs were also similar to each other with respect to tumor cell states, with 92% of tumor cells being MART1+ PMEL+." (PMID 40667360, 2025). "PMEL, also known as gp100, participates in cancer immune infiltration and tumor-specific immunotherapy, especially in targeting T cell therapy." (PMID 38410384, 2024). "We identified 15 melanocyte protein PMEL (GP100)-derived epitopes in the 3784Mel cell line derived from the tumor of a patient whose tumor-infiltrating CD8+ lymphocytes have been previously shown to recognize the GP100 antigen." (PMID 34391887, 2021). "In the case of PMEL/gp100 and Tyrosinase Ags, their expression was verified by immunohistochemical staining in tumor biopsies (ST5)." (PMID 32582212, 2020). "In a previous study, we utilised ‘CARaMEL’ dual‐specific T cells, expressing a CAR specific for Her2 tumour antigen, and a T‐cell receptor (TCR) specific for a strong, tumour‐unrelated immunogen, the melanocyte protein gp100 (also known as pMEL)." (PMID 32704371, 2020). "These tumours showed similar patterns of immunoreactivityto tumours obtained from whole sphere populations when stained with antibodies against PMEL, SMA, PDGFRβ, CATHEPSIN K, NG2 and S100, as well as displayed E-CADHERIN positive epithelial structures." (PMID 29133867, 2017). "The molecular bases of the association of MGRN1, PMEL, MLANA, and TYRP1 expression within the tumor and patient survival remain speculative." (PMID 40004203, 2025). "We identified UM-associated hybrid cells based on co-expression of melanocytic tumor proteins: Microphthalmia-associated transcription factor (MITF), Tyrosinase (TYR), Melan-A (MLANA), premelanosome protein (PMEL, GP100), 5-hydroxytryptamine receptor 2B (HTR2B) and the pan-leukocyte marker CD45." (PMID 38106024, 2023). "Approximately 15% of cells in our allograft tumours exhibited immunoreactivity for PMEL." (PMID 29133867, 2017). "The marker genes S100B, PMEL, and MLANA showed significantly high expression in tumor cells in the SKCM_GSE115978_aPD1 dataset." (PMID 38911384, 2024). "In particular, the BACE1/2 dependent maturation of amyloidogenic proteins such as APP or PMEL, has been shown to affect TME cells behavior and to act both in paracrine and autocrine way driving tumor proliferation and progression." (PMID 33926496, 2021). "UM cells express tumor-specific antigens, including the Melanoma Antigen Gene (MAGE) family proteins, premelanosome protein gp100, and tyrosinase." (PMID 33194647, 2020). "Expression levels of many proteins were altered with resistance development including gp100/PMEL, CD171/L1CAM, GAB2, mTOR and PI3K-p85 which have been previously shown to be upregulated in tumors including CMM and promoting tumor progression." (PMID 33082316, 2020). "UM cells express tumor-specific antigens, including the Melanoma Antigen Gene (MAGE) family proteins, premelanosome protein gp100, and tyrosinase, that are recognized by elements of the immune system." (PMID 31750244, 2019). "In this feasibility study, several proteins were identified that positively correlated to tumor tissue content including IF6, ARF4, MUC18, UBC12, CSPG4, PCNA, PMEL and MAGD2." (PMID 28445515, 2017). "Allograft tumours from SC2 and SC4 express melanocyte genes and the proteins PMEL, MiTF and CATHEPSIN K." (PMID 29133867, 2017).
tumor (continued). "By IHC and immunoblotting, STP tumor cells showed strong expression of nuclear TFE3, the canonical TFE3 target GPNMB, as well as expression of melanocytic and lysosomal markers (PMEL, MelanA and Cathepsin K) commonly upregulated in human MiT/TFE-related neoplasms." (PMID 41044182, 2025). "No histological similarities with renal AML were evident and tumours showed no immunoreactivity for PMEL, S100 or NG2." (PMID 29133867, 2017). "In accordance with our previous data, APOE, PMEL, QPCT, and SORT1 were specifically secreted in all metastatic tumor cell lines together with proteins involved in ECM deposition and adhesive proteins supporting the hypothesis of amyloid fibril deposition (Fig EV2F)." (PMID 32749065, 2020). "Similarly to the other tumours generated in this study, these allograft tumours stained positively for PMEL, CATHEPSIN K, PDGFRβ, SMA and VIMENTIN, expressed PMEL by western blotting, and exhibited a similar frequency of PMEL expressing cells." (PMID 29133867, 2017).
cancer (134 papers, 2002 to 2026). A tumor composed of atypical neoplastic, often pleomorphic cells that invade other tissues. "We loaded ImmDCs and MaDCs from three donors with a mixture of equal amounts of seven long peptides (25–40 mers) from the known cancer associated antigens PMEL, MAGEA4, MLANA, and CTAG1A (NY-ESO1)." (PMID 32983136, 2020). "The cancer cell modules (I) of the two samples are characterized by distinct marker genes, i.e., PMEL, ATP1A1, and SPP1 in sample 1 whereas S100B and PSAP in sample 2, in line with previous studies." (PMID 40033360, 2025). "Top three mostly used canvaxgens are PMEL, MLANA and CTAG1B, often targeting multiple cancer types." (PMID 38204924, 2024).
eye disorder (1 paper, 2021). A non-neoplastic or neoplastic disorder that affects the eye. "The mutation in PMEL gene has pleiotropic effects and is also causative of equine multiple congenital ocular anomalies (MCOA) syndrome, which is a heritable eye disorder." (PMID 33226152, 2021).
PMEL also shares sentences with these, for which no sentence is quoted: angiomyolipoma (44 papers); clear cell sarcoma (16); renal cell carcinoma (15); sarcoma (13); leiomyosarcoma (12); glioma (11); schwannoma (11); smooth muscle tumor (9); breast carcinoma (8); lymphoma (8); amelanotic melanoma (7); glioblastoma (7); leiomyoma (7); rhabdomyosarcoma (7); brain tumors (6); cyst (6); mesenchymal tumors (6); dysplastic nevi (5); endometrial stromal sarcoma (5); infection (5); melanocytic neoplasm (5); small cell lung carcinoma (5); squamous cell carcinoma (5); angiosarcoma (4); breast tumors (4); clear cell renal cell carcinomas (4); Ewing sarcoma (4); gastrointestinal stromal tumor (4); malignant peripheral nerve sheath tumor (4); neuroblastoma (4).
A further 161 diseases each share a sentence with PMEL in 4 papers or fewer.